EGFR (epidermal growth factor receptor)
Diseases named in the same sentence as EGFR in open-access papers (continued):
Sharing a sentence is not in itself a finding about the gene and the disease.
cancer (continued). "We propose that the cancer cells utilize a double-secure way to down-regulate cell surface EGFR in response to stress conditions." (PMID 27034618, 2016). "We observed that EGFR, a validated cancer drug target, affects the largest number of components under activating and inactivating perturbations." (PMID 26904540, 2016). "Overexpression or amplification of the EGFR generally results in cancers with increased aggressiveness, higher rates of metastases, and worse patient prognosis." (PMID 27153091, 2016). "The fact that Netrin-1 fosters HCV entry through fostering EGFR activation is in agreement with previous reports on the involvement of Netrin-1 in cancers, in which dysregulated EGFR expression and signaling play a major role." (PMID 27031829, 2016). "Stage IV cancer, wild type EGFR status and NLR≥3.7 were independent prognostic factors for worse PFS." (PMID 27029035, 2016). "Over the decades, many bacterial- or plant-based immunotoxins have been developed with the goal of targeting the broad range of cancers reliant upon EGFR overexpression." (PMID 27153091, 2016). "siRNA-mediated suppression of CD73 in cancer cells led to downregulation of p-EGFR and p-Src, while SSG (a Src activator) treatment led to a further decrease in p-EGFR expression." (PMID 27557512, 2016). "The epidermal growth factor receptor (EGFR) has been increasingly recognized as a molecular target in cancer therapy." (PMID 27391842, 2016). "This review summarizes much of the past and current work in the development of immunotoxins for targeting EGFR-driven cancers." (PMID 27153091, 2016). "The MET and EGFR receptors are actionable targets due to their high expression in TNBC; however crosstalk between MET and EGFR has been implicated in therapeutic resistance to single agent use of MET or EGFR inhibitors in several cancer types." (PMID 27655711, 2016). "In cancer, EGFR has been shown to have growth inhibitory effects as it induced the expression of IRF-1 via phosphorylation of STAT1 and STAT3." (PMID 26881744, 2016). "It opens new avenues of investigations of multiple inhibitory targets (ER-α, IGF-1R and EGFR) for wet lab experiments as well as provided valuable insights in the treatment of cancers such as BC." (PMID 27781158, 2016). "Several lines of evidence have proved that blockade of the EGFR pathway can increase the response rate of radiotherapy or chemotherapy in EGFR-activated carcinomas." (PMID 27626176, 2016). "Noticeably, this transcript was also observed in carcinoma cell lines that show EGFR gene amplification." (PMID 27104520, 2016). "A signaling pathway that is frequently deregulated in human carcinomas and has been explored as a therapeutic target involves the activation of the epidermal growth factor receptor (EGFR)." (PMID 27248176, 2016). "Molecular cloning of EGFR also revealed a close similarity with the viral v-erbB oncogene, yielding the first indication of a link between growth factor receptors and cancer." (PMID 26635612, 2015). "Although gefitinib has effects on EGFR activated cancer cells, apparently most TNBC cells with elevated level of EGFR exhibit resistance to EGFR inhibitor treatment." (PMID 25955731, 2015). "In cancer, EGFR signalling is often deregulated, contributing to tumorigenesis, therapy resistance and poor patient survival." (PMID 26066081, 2015). "Recent studies revealed that STATs played an important role in maintaining EGFR-mediated cancer cell proliferation." (PMID 26106437, 2015). "Hepatocyte growth factor (HGF) confers EGFR TKI resistance by inducing two cancer-promoting functions." (PMID 26405162, 2015). "In CM, NGF signalling genes display a dense nature of co-membership with other signalling events and maximally co-membered (n = 37) with “signalling by FGFR in disease”, “signalling by EGFR in cancer” and “signalling by PDGF”." (PMID 26558755, 2015).
cancer (continued). "One highly investigated cancer antigen for treatment of solid tumors is the epidermal growth factor receptor (EGFR)." (PMID 26579120, 2015). "Epithelial growth factor receptor (EGFR), which is also known as erbB1 or HER1, is the first growth factor receptor to be proposed as a target for anti-cancer therapy." (PMID 25542231, 2015). "MUC1, in association with other molecules such as β-catenin, NF-kB p65 or EGFR, regulates transcription of several genes responsible for progression and invasiveness of cancer." (PMID 25675408, 2015). "As EGFR can be overexpressed in a wide range of tumors and it correlates with poor survival and cancer progression, inhibition of EGFR signaling pathway will be a promising therapeutic target." (PMID 25542231, 2015). "To address this aim we developed isogenic pairs of drug-sensitive and -resistant cancer cells, a strategy which has already been successfully applied to model EGFR-TKIs resistance in NSCLC." (PMID 26015408, 2015). "Small molecule TKIs inhibit cancer growth by suppressing EGFR tyrosine phosphorylation at multiple residues." (PMID 26079946, 2015). "To address this question, we first examined the constitutive activity of EGFR in several cancer cell lines (PC3, DU145, A549, and HT29) cultured in serum free medium for 24 hrs." (PMID 26378037, 2015). "A number of cancers are characterised by over-expression of (EGFR), a membrane protein which mediates cell growth, proliferation and differentiation in multiple tissues." (PMID 26516922, 2015). "The importance of the human epidermal growth factor receptor (HER, also known as ErbB) family in the development and progression of various cancers is widely recognized." (PMID 26068969, 2015). "A significant decrease in the invasion ability of cancer cells confronted with IL-10-stimulated macrophages was observed upon EGFR silencing, even when comparing with AGS cells transfected with Lipofectamine only." (PMID 26043921, 2015). "Here, we characterize the molecular changes that occur in NSCLC to SCLC transformed TKI-resistant EGFR mutant cancers." (PMID 25758528, 2015). "Among the seven patients, five showed intense EGFR overexpression in cancer tissue compared with normal tissue." (PMID 26655729, 2015). "Treatment of mouse models of human cancer with the EGFR targeting mAb cetuximab induced decreases in FLT uptake." (PMID 26460961, 2015). "GPER/EGFR/ERK signaling upregulates β1-integrin expression and activates downstream kinases, which contributes to cancer-associated fibroblast-induced cell migration and epithelial-mesenchymal transition, in MCF-7R cells." (PMID 25990368, 2015). "Aberrant activation of the EGFR-Ras-Raf-MEK-ERK cascade is believed to contribute to cancer development and progression." (PMID 25776829, 2015). "EGFR degradation is a major desensitization process that can prevent receptor hyperactivation commonly found in cancer." (PMID 26568478, 2015). "EGFR tyrosine kinase inhibitors (EGFR-TKIs), such as erlotinib or gefitinib, mainly function through blocking the ATP-binding pocket of the EGFR and suppressing two major signaling pathways in cancer - PI3K/Akt and Ras/MAPK pathway." (PMID 26593208, 2015). "The epidermal growth factor receptor (EGFR) is a member of the ErbB family that is involved in a number of processes responsible for cancer development and progression such as angiogenesis, apoptosis, cell proliferation and metastatic spread." (PMID 26041145, 2015). "There is also evidence that under hypoxia cancer cells can sustain EGFR-mediated signaling through reduced EGFR endocytosis and the preservation of the receptor in the endosome." (PMID 25885672, 2015). "Earlier studies have identified miRNAs that targeted components of the EGFR signaling pathway; however, few studies have explored the miRNA alterations in mutated KRAS tumors and their impact on cancer progression." (PMID 25756961, 2015).
cancer (continued). "Ability of soluble ligands to increase the levels of nuclear EGFR in cancer cells can explain the acquired resistance to anticancer drugs." (PMID 26016774, 2015). "Many cancer cells addicted oncogenes such as mutant EGFR, amplified HER2 and fused EML4-ALK rely on Hsp90 for their conformational maturation." (PMID 26097875, 2015). "Our data provide novel mechanistic insights into the response and resistance of cancer cells to EGFR-targeted therapy from an energy homeostasis point of view." (PMID 25871473, 2015). "The EGFR TK domain has been identified as suitable target in cancer therapy and drugs such as erlotinib have been used for treatment of cancer." (PMID 26041145, 2015). "It is also known that the MAPK pathway is regulated by EGFR signaling in cancer cell growth and that resistance to cisplatin chemotherapy has been shown to involve MAPK signaling." (PMID 26491668, 2015). "Ras family proteins are essential downstream components of the EGFR/Ras/MAPK signaling pathways and Ras mutations are frequently detected in several cancers, thereby limiting the clinical benefit of EGFR inhibitors." (PMID 26036637, 2015). "We have demonstrated a critical role for integrin and epidermal growth factor receptor (EGFR) signalling in inherent resistance of cancer cells to cixutumumab, a fully human IgG1 monoclonal antibody against IGF-1R11." (PMID 26465273, 2015). "On the other hand, 70–75 % colorectal cancer patients overexpress EGFR, more than other cancer patients like NSCLC with 60 %." (PMID 25542231, 2015). "Preclinical studies show that some cancers sensitive to anti-EGFR therapy also abundantly express EGFR ligands, especially amphiregulin." (PMID 26569500, 2015). "Several cytotoxic anticancer drugs inhibit DNA replication and/or mitosis, while EGFR tyrosine kinase inhibitors inactivate EGFR signalling in cancer cell." (PMID 26439264, 2015). "For instance, pathways like “cell cycle”, “signalling by WNT in cancer”, “PI3K/Akt signalling”, “EGFR signalling in cancer” and “MAPK signalling” have R > 3.50 in both the metastatic networks." (PMID 26558755, 2015). "In several carcinoma cell lines, but also in an HCC cell lines, HGF was recently found to inhibit EGFR tyrosine kinase activity and that this kinase-inactive EGFR stabilizes cancer-related proteins." (PMID 26729094, 2015). "The reports indicated that alcohol extracts of the centipede S. subspinipes mutilans (AECS) inhibits A375 cell proliferation, as well as shows anticancer activity against epidermal growth factor receptor (EGFR)-dependent cancers." (PMID 26593947, 2015). "It is well known that EGFR participates in diverse cellular processes such as growth, differentiation, tumorigenesis, invasion and metastasis of cancer." (PMID 26182292, 2015). "Because CD151 or its associated LB integrins have been shown to functionally collaborate with EGFR in other cancer types, these highly EGF-responsive cell lines were adopted for subsequent functional analyses." (PMID 26377974, 2015). "Collectively, our findings indicate that the EGFR-L858R mutant increases cancer cell invasive ability and MPE formation through ERK-dependent activation of the CXCL12-CXCR4 axis." (PMID 26338423, 2015). "In a recent study, the EGFR inhibitor erlotinib was demonstrated to sensitize basal-like cancer cells (BT-20)." (PMID 26001967, 2015). "Treating these cancers with a drug called erlotinib inhibits EGFR and makes thetumors shrink dramatically, but the tumors will usually re-grow because any tumorcells that survive often become resistant to the drug." (PMID 25686219, 2015). "Previous studies have demonstrated that EGFR overexpression promotes cancer cell survival, proliferation, migration, and invasion." (PMID 26503469, 2015).
cancer (continued). "In conclusion, the pretreatment of EGFR tyrosine kinase inhibitors promote pro-caspase-8 dimerization that sensitizes cancer cells to DNA-damaging agents." (PMID 26036637, 2015). "Together, these findings suggest that SFKs and EGFR cooperate in acquired resistance to Cetuximab, providing a strong rationale for combinatorial strategies against SFKs and EGFR in the treatment of cancer." (PMID 26087188, 2015). "Specific EGFR inhibitors, such as erlotinib, gefitinib, and the monoclonal antibody cetuximab are effective for treating cancer." (PMID 25738771, 2015). "Cetuximab, an anti-EGFR immunoglobulin G1 chimeric mAb, has been approved and widely used in the clinical treatment of colorectal carcinoma, as well as cancers of the head and neck." (PMID 26491668, 2015). "In cancer cells, EGFR activation is important in maintaining the metabolic homeostasis and stimulates proliferation, invasion, angiogenesis, survival, decreased apoptosis, migration, differentiation and adhesion." (PMID 25948104, 2015). "Epidermal growth factor receptor-tyrosine kinase inhibitor (EGFR-TKI) is one of the most successful targeting agents used to treat cancer." (PMID 25780909, 2015). "The EGFR and its ligands represent ‘druggable’ targets which when inhibited result in downregulation of growth factor pathways and thus anti-cancer effect." (PMID 26478746, 2015). "Comment on: Takagi S, Banno H, Hayashi A, Tamura T, Ishikawa T, Ohta Y. HER2 and HER3 cooperatively regulate cancer cell growth and determine sensitivity to the novel investigational EGFR/HER2 kinase inhibitor TAK-285." (PMID 25655645, 2015). "Further, increased neuroendocrine marker and decreased EGFR expression as well as greater sensitivity to BCL2 family inhibition are observed in resistant SCLC transformed cancers compared with resistant NSCLCs." (PMID 25758528, 2015). "We have previously reported that FUT4 siRNA mediated deactivation of EGFR/MAPK pathway to inhibit cancer cell proliferation." (PMID 25672851, 2015). "With their relative success in CML, TKIs which target other oncogenic tyrosine kinases have been tested in other cancers, such as lapatinib in EGFR-expressing GBM." (PMID 26136341, 2015). "There are results also demonstrate that combination of CK2 inhibitor CX-4945 with erlotinib (EGFR tyrosine kinase inhibitor) results in synergistic killing of cancer cells by attenuating the PI3K-Akt-mTOR pathway." (PMID 26172393, 2015). "EGFR and its downstream signaling pathway is a key regulator of cell proliferation and it is frequently deregulated in cancer." (PMID 25544346, 2015). "Up-regulation of EGFR signaling activity occurs in many types of cancers and is thus an attractive target for contemporary drug development." (PMID 26370727, 2015). "EGFR inhibitors have been widely used in anti-cancer therapy; however, they are inefficient in mCRCs harboring activating KRAS mutations, which remains an obstacle to the effective treatment of mCRC." (PMID 26418750, 2015). "This PGE2 liberated participated in the survival and proliferation of surviving cancer cells by activating several pathways, including EGFR and β-catenin." (PMID 25749386, 2015). "In the clinic, the current approaches of anti-EGFR therapies have been facing critical challenges of innate resistance and inevitable acquired resistance in EGFR-positive cancers." (PMID 26378037, 2015). "Using the MRI technique, these investigators demonstrated that ScFvEGFR-IO specifically bound to and was internalized by EGFR-expressing cancer cells." (PMID 26579537, 2015). "Epidermal growth factor receptor (EGFR) signaling plays an important role in various cancers, including HCC." (PMID 26436086, 2015). "Because overcoming resistance is an unmet need to treat human cancer, we performed an MTT screening for synthetic lethality with a small library of various RTKIs in MDA-MB-231 cells in the presence of an EGFR inhibitor gefitinib." (PMID 25955731, 2015).
cancer (continued). "Our data here and others’14 suggest that EGFR TKI treatment potentiates cisplatin-induced cytotoxicity in various cancer types." (PMID 26568478, 2015). "STAT3 is an oncogene that is hyper-activated in many cancers, including HNSCC, where STAT3 hyper-activation is associated with decreased survival and emergent resistance to EGFR-targeted therapy." (PMID 26267899, 2015). "The overexpressed proteins including epidermal growth factor receptor, glypicans and epithelial cell adhesion molecule (EpCAM) have widespread roles in numerous cancers, thereby supporting the authenticity of our SILAC screen." (PMID 25630468, 2015). "Interaction has been found between Flotillins and EGFR in cancer cells and Flot-2 becomes Tyr- phosphorylated by Src kinase based on EGFR activation." (PMID 26161893, 2015). "Similar to other cancers, recurrent amplification of 7p11.2, 8q24.21, and 11q13.2, harboring EGFR, MYC, and CCND1, has previously been reported in ESCC." (PMID 26465158, 2015). "The BRAF inhibitor vemurafenib lacks efficacy in this cancer, due to a feedback regulatory mechanism resulting in high EGFR activity." (PMID 26018524, 2015). "Taken together, these results demonstrate that ANO1 regulates EGFR-protein levels in cancer cells by a posttranslational, degradation-independent mechanism, suggesting a role of ANO1 in stabilizing EGFR in the cells." (PMID 25823819, 2015). "We here aim to study the differential gene expression in EGFR inhibitor-sensitive vs. resistant cancer cell lines." (PMID 25948104, 2015). "The emerging role of EGFR signaling in cancers has led the development of anti-EGFR agents, including tyrosine kinase inhibitors (TKIs) and monoclonal antibodies against EGFR." (PMID 26064956, 2015). "The epidermal growth factor receptor (EGFR) which expresses in a variety of human cancer cells, including ovarian, breast, colon, prostate and NSCLC, is a transmembrane receptor protein identified primarily on cells of epithelial origin." (PMID 26057469, 2015). "Cancer cells can exploit diverse interrelated signaling components to amplify oncogenic EGFR-driven network activity." (PMID 25885672, 2015). "Though EGFR inhibitors have shown promise in the clinical practice against some cancers, adaptive resistance remains a major problem." (PMID 25894462, 2015). "This protein encourages cells to divide and themutations can lead to the cancer cells producing more EGFR, or producing a form ofthe protein that is more active." (PMID 25686219, 2015). "In our long-term in vivo efficacy study, we demonstrated that licofelone and gefitinib can target COX-2, 5-LOX, EGFR, and cancer stem cell marker DclK1, and can potently inhibit PanIN progression to PDAC without any side effects." (PMID 26429877, 2015). "Studies have found that some EGFR IHC results in various cancer types are dependent on the type of antibody used." (PMID 26149458, 2015). "One of the downstream modulators of EGFR signalling PIK3CA, exhibits activating mutations in brain metastases from breast (2/12) and other cancers (2/9)." (PMID 25969993, 2015). "Pretreatment mRNA levels of Bim predicted the capacity of EGFR inhibitors to induce apoptosis in EGFR-mutant cancer cells." (PMID 26405162, 2015). "Further study of sensitive and resistant cancer cell lines responses to additional EGFR inhibitors will improve our understanding of drug resistance development and thus lead to improved anticancer treatment strategies." (PMID 25948104, 2015). "Here, using gain- and loss-of-function approaches, we demonstrated that the EGFR-L858R mutant enhances cancer cell invasion compared with EGFR-WT." (PMID 26338423, 2015). "WB-308 also possesses a novel chemical backbone structure, which is substantially different from known typical EGFR-TKIs, which provides a new structural scaffold for future modification and development of potential anti-cancer agents against NSCLC." (PMID 25730907, 2015).